PERCC1 (proline and glutamate rich with coiled coil 1)
Description:
Plays a critical role in intestinal function. Acts by promoting the development of enteroendocrine cells (EECs) of the gastrointestinal tract and pancreas (By similarity). It is thereby required for normal enteroendocrine peptide hormone secretion (By similarity).
Synonyms: DIAR11; ICR; gs104
Gene: Protein-coding gene on chromosome 16 (1,431,078 to 1,434,441, forward strand). Ensembl gene ENSG00000284395.
Gene Ontology:
Biological process: digestive tract morphogenesis; enteroendocrine cell differentiation
Homologues: Orthologues: chimpanzee PERCC1 (95% identical), pig PERCC1 (70% identical), mouse Percc1 (66% identical), rat Percc1 (66% identical), dog PERCC1 (63% identical), tropical clawed frog XB940087 (39% identical).
Diseases named in the same sentence as PERCC1 in open-access papers:
PERCC1 is named in the same sentence as 6 diseases in open-access papers, as found by Europe PMC text mining. Sharing a sentence is not in itself a finding about the gene and the disease. The quoted sentences say what the papers report.
congenital enteropathy (2 papers, 2023 to 2026). "We present herein a point mutation in PERCC1 in association with a congenital enteropathy in two unrelated probands of Irish descent and discuss their molecular and phenotypic features." (PMID 36076104, 2023).
hepatocellular carcinoma (1 paper, 2022). A malignant tumor that arises from hepatocytes. "Diseases associated with GNPTG include mucolipidosis III gamma and mucolipidosis, and those associated with PERCC1 include diarrhea 11, malabsorptive, congenital, and hepatocellular carcinoma." (PMID 35990977, 2022).
PERCC1 also shares sentences with these, for which no sentence is quoted: enteropathy (2 papers); genetic disorders (1); mucolipidosis (1); mucolipidosis III gamma (1).